CD34 (CD34 molecule)
Diseases named in the same sentence as CD34 in open-access papers (continued):
Sharing a sentence is not in itself a finding about the gene and the disease.
tumor (continued). "As SOD3 regulated HIF-2α stability in mouse EC, we studied the expression of these two genes in the CRC TMA, using CD34 as a label of tumor-associated ECs; 55.4% of CD34+ ECs were SOD3 stained." (PMID 29422508, 2018). "Here, IDO expression was predominantly observed in mature (CD31+/CD34+/α-sma+) tumor-associated blood vessels and in two patients in lymphatic (podoplanin-positive) vessels." (PMID 30050535, 2018). "Orthotopic injection of 200–106 CD34+ cells from Tgfbr2 cKO anorectal SCC into recipient Nu/Nu mice caused secondary tumor formation with 100% efficiency (n = 89)." (PMID 28219480, 2017). "The Kaplan-Meier survival curve indicates that patient death is associated with tumor M staging (P = 0.011), bleeding (P = 0.023), R0 resection (P = 0.024), and positive expression of CD34 (P = 0.007)." (PMID 28589146, 2017). "CD34 is a molecule related to the abluminal endothelial microprocess that causes vascular sprouting in the tumor’s stroma in the angiogenesis stage, used in measuring microvessel density." (PMID 27583351, 2017). "Vimentin and CD34 are associated with tumor growth, invasion and metastasis, and Ki-67 is a marker of tumor cell proliferation." (PMID 26871290, 2016). "BM has been replaced by PBSC as a stem cell source in MRD and MUD SCT because of the higher engraftment rates due to the larger number of CD34+ stem cells and because of a potential higher graft versus tumor effect linked to a larger number of T cells." (PMID 27118973, 2016). "C1q expression within newly formed tumour-associated vascular endothelia was further confirmed by double-staining with CD34, an endothelial marker." (PMID 26831747, 2016). "The researchers interpreted this difference in staining with CD34 in MPTT cases to be associated with the differentiation grade of the tumor and the increase in the loss of CD34 staining as the differentiation grade decreases." (PMID 26064131, 2015). "Instead, CD34+ vessel number was positively associated with the presence of CD68 in tumor stroma, furthering the notion that S100A9 promotes angiogenesis in vivo through increased macrophage recruitment." (PMID 26315114, 2015). "CD34 is a sensitive marker of the vascular endothelium and strong CD34 staining is usually associated with tumor relapse or metastasis." (PMID 25120721, 2014). "All genotypes displayed positive staining for Ki67, TUNEL, and CD34, suggesting that loss of a single copy of Ptprd is sufficient to achieve tumor proliferation, apoptosis, and angiogenesis respectively." (PMID 25138050, 2014). "Increased levels of antibodies to endoglin, CD31 and CD34 are associated with progression-free survival tumor grade and metastasis." (PMID 24507660, 2014). "Univariate analysis revealed that sex, tumor size, mitotic rate, risk grade, CD34 expression, and adjacent involvement were predictors of OS or RFS." (PMID 25403624, 2014). "The expression of CD44 and CD133 decreased and, to our surprise, human-specific endothelial-associated marker CD34 increased in the tumor nodules." (PMID 24280306, 2013). "The tumour Ki-67 proliferation index was directly associated with CD34+ microvessel density (P=0.05) and neo-adjuvant therapy (P<0.001)." (PMID 22240784, 2012). "CD34+ fibrocytes are constitutive elements of the connective tissue, where they play a role in matrix synthesis and tumor-associated stromal remodeling." (PMID 23166536, 2012). "After transplantation into mice with severe combined immune deficiency (SCID), these CD34+/CD38− cells can form tumors that phenotypically resemble the patient’s original tumor, indicating that they are tumorigenic." (PMID 23443123, 2012). "Overexpression of angiogenic genes such as VEGF and CD34 has been shown to be associated with enhanced tumorigenicity and tumor metastatic potential." (PMID 23554730, 2012).
tumor (continued). "The difference at the later time-point can be attributed to CD34 loss on hematopoietic cells and likely reflects a reduced capacity of Cd34−/− mast cells and eosinophils to dampen tumor growth and induce immune tumor rejection." (PMID 21494591, 2011). "During embryonic vascular development, CD34 and podocalyxin colocalize to sites of lumen formation in the embryonic aorta and adult tumor-associated vessels." (PMID 21494591, 2011). "It is expressed in normal hematopoietic CD34+ cells and has been associated with a subpopulation of tumor cells that includes tumor stem cells." (PMID 21526180, 2011). "In contrast, at a later time-point (day 19) tumor growth is increased in Cd34−/− animals, associated with reduced intra-tumor mast cell numbers." (PMID 21494591, 2011). "Lastly, the staining of tumor cells in our case with antibodies to CD34, a 115-kDa transmembrane glycoprotein associated with cellular interaction and adhesion, is an additional finding compatible with the diagnosis of AMF." (PMID 20202207, 2010). "The expression of CD34 by tumour-associated LECs was identified in colon cancer, breast cancer, lung cancer and melanoma." (PMID 17117184, 2006). "At the same time, ALA increased the production of CD66b– CD14+ monocytes, while decreased the production of CD66b+CD14– neutrophils and CD66b+CD14+ proinflammatory monocytes or antigen-presenting cells (APCs)-like tumor associate neutrophil like cells derived from CD34+ HSPCs." (PMID 38589882, 2024). "CD34 positive fibroblasts’ presence was highly associated with normal breast stroma, while αSMA-positive CAFs were intensely discussed as being specific to the BC tumor stroma." (PMID 37568639, 2023). "Furthermore, an increased level of CCL9 was associated with enhanced recruitment of CD34+ immature myeloid cells (iMCs) from bone marrow to the tumor site." (PMID 37185750, 2023). "However, CD34 expression has been associated with increased tumor aggressiveness and resistance to chemotherapy in some types of cancer." (PMID 37241170, 2023). "Our previous investigations utilizing CD34 and α-smooth muscle actin (αSMA) immunohistochemistry revealed a reduction in CD34-positive cancer-associated fibroblasts (CAFs) and a rise in αSMA-positive CAFs within the tumor stroma." (PMID 37568639, 2023). "In another experiment from that same study, NSG-S mice that retained myeloid cells after receiving CD33 KO CD34+ cells and a CD33 directed CAR, experienced greater reduction in tumor burden and less toxicity compared to mice that loss myeloid cells after receiving control CD34+ cells." (PMID 36831198, 2023). "As one type of antigen-presenting cells, loss of CD34+-fibrocytes may promote immune evasion of tumor." (PMID 35712477, 2022). "The CD34 is a protein, the expression of which is observed in early hematopoietic and vascular-associated tissue, therefore, it was used in order to check the presence of coagulative tumor cell necrosis." (PMID 35454875, 2022). "Furthermore, cutaneous CSCs maintenance is dependent on Wnt/β-catenin signaling, and ablation of the β-catenin gene results in the loss of CD34+ CSCs and complete tumor regression." (PMID 34345013, 2021). "Tumor angiogenesis as assessed by CD31 and CD34 staining is associated with tumor growth." (PMID 34942951, 2021). "BMDCs contribute as various cells in TME such as αSMA-positive cancer-associated fibroblasts (CAFs), CD34-positive tumor-associated endothelial cells (TECs), and CD11b-positive tumor-associated macrophages (TAMs) and facilitate tumorigenesis, invasion, and metastasis." (PMID 35008304, 2021). "They claimed that there is a considerable association between CD34 expression and tumor metastasis." (PMID 33383808, 2020).
tumor (continued). "We also studied the frequency of other BM-residing cells that have been implicated in tumor context, including hematopoietic stem and progenitor cells (HSPCs), T-cells and B-cells which were detected by expression of cell surface markers CD34/CD45, CD3 and CD19, respectively." (PMID 33147765, 2020). "CD34+ fibroblasts are constitutive stromal components of virtually all organs, including the mammary stroma, being involved in matrix synthesis, antigen presentation, and tumor-associated stromal remodeling." (PMID 32435886, 2020). "Tumor island-associated vessels expressed CD34 and, thus, were confirmed to be endothelial cells." (PMID 31336612, 2019). "IDO-positive tumor-associated vessels were studied by 7-color multiplex immunohistochemistry using the markers CD31/CD34 (endothelial cell markers), podoplanin (lymphatic endothelial cell marker), α-sma (perivascular cell marker), galectin-1 (activated endothelial cell marker), and IDO." (PMID 30050535, 2018). "Previous research studies found an association between CD34 loss and higher-grade tumours and decreased CD34 expression is also linked to recurrent tumours, a finding confirmed by our data: we observed a very low (<10%) CD34-expression in most of our recurrent cases (3/5, 60%)." (PMID 30183767, 2018). "Associations were examined between these TILs, CD34+ tumor blood vessels, and clinical outcomes." (PMID 29163521, 2017). "Important evidence that PDPN-positive fibroblasts can affect the formation of blood vessels comes from the clinical studies as the presence of large numbers of PDPN-positive CAFs was associated with numerous CD34-positive blood vessels in tumor stroma of IDC samples." (PMID 28938000, 2017). "However, when using supervised clustering analysis in the CD34+ cells a subset of differentially methylated CpG sites, frequently located in tumor suppressors and oncogenes, were found in ASXL1 mutated cases." (PMID 28754985, 2017). "Moreover, co‐staining for CK7 and the blood vessel marker CD34 highlighted the presence of blood vessels in these tumours that were still associated with alveolar epithelial cells, showing that these tumours incorporate alveolar capillaries." (PMID 27859259, 2017). "In addition, β-catenin-deficient tumor cells devoid of the CD34+ CSCs were unable to propagate secondary tumors, and conversely tamoxifen-induced expression of a nondegradable β-catenin in the skin sufficiently expanded the bulge CSC's population." (PMID 28356914, 2017). "Moreover, some authors have postulated that a loss of CD34 staining is related to a decrease in the differentiation of the tumor." (PMID 27403361, 2016). "We believe that several mechanisms may explain the promotion of tumor invasion in breast tissue induced by the loss of CD34 fibrocytes and the gain of SMA myofibroblasts." (PMID 25011545, 2014). "The HNSCC patients were then evaluated for whether tumor stage was associated with the extent to which CD34+ cells were increased." (PMID 24202334, 2013). "Our result presented that Fibrocyte_CD34 and CAF_C3 may be associated with the tumor progression." (PMID 40725006, 2025). "Therefore, a reduction in CD34 positive microvessels may be associated with tumor development in LUAD." (PMID 39906069, 2025). "In one study, immune-deficient transgenic mice (NSG-S) injected with human CD34+ cells experienced greater reduction in tumor burden compared to their immune-incompetent counterparts, suggesting that normal hematopoiesis may provide some clinical benefit with CAR T response in vivo." (PMID 36831198, 2023). "Furthermore, two molecules associated with the cancer stroma, i.e., CD34 (to label blood vessels) and D2-40 (to label lymph vessels), were assessed, and we found that tumours in the LAG-3 cluster were less dependent on the development of lymph vessels than those in the TIGIT cluster." (PMID 34545095, 2021). "Moreover, loss of CD34+ CAFs might influence the dedifferentiation of the NSCLC tumor from its cell origin." (PMID 31760702, 2020).
tumor (continued). "In conclusion, our finding indicated that NK cells differentiated from CD34+ cells isolated from cord blood were able to induce apoptosis and has shown increased antitumor potential in vitro against different cancer cells besides cause down regulation of survivin gene expression in tumor cells." (PMID 32592353, 2020). "The use of purified CD34+ stem cells may offer an opportunity to reshape the repertoire of the reconstituting ‘naïve’ T lymphocytes to include tumour-associated self-antigens, thus overcoming any tumour-induced suppression of antitumour immunity." (PMID 12799629, 2003). "The internodular and perinodular tumor stroma exhibited varying levels of CD34 antigen expression, as well as morphological diversity and differences in physical distribution across regions of the tumor mass." (PMID 41597444, 2026). "The juxtatumoral zone can be seen as an adaptive response of the adjacent skin, manifesting as a compressed reticular dermis containing highly CD34-positive stromal cells that surround the tumor masses." (PMID 41597444, 2026). "Compared to the pattern of CD34 expression in the region of tumor, the juxtatumoral zone of reticular dermis shows strong CD34 immunohistochemical positivity in stromal cells and microvascular blood vessels in all examined BCCs." (PMID 41597444, 2026). "In juxtatumoral zone, the reticular dermis surrounding the tumor mass demonstrated CD34 immunoreactivity." (PMID 41597444, 2026). "Emergency laparotomy and tumor resection were performed, with histopathological examination confirming a high-risk GIST with positive c-Kit (CD117) and CD34 immunostaining." (PMID 41658783, 2026). "The findings reveal the value of comprehensive tumor microenvironment analyses, highlighting B cells, CD34+ B cells, monocytes, and NK cells as key prognostic indicators." (PMID 41511965, 2026). "Immunohistochemical staining demonstrated that the tumor cells were positive for CD34, desmin, androgen receptor, and progesterone receptor." (PMID 41529035, 2026). "Exceptions were observed in parts of a few cases of nodular BCCs, in which extravascular CD34 immunoreactivity was detected in fibroblasts of the tumor stroma." (PMID 41597444, 2026). "In histologically unaltered dermis, present beneath and around the tumor lesion, the staining pattern for the CD34 antigen corresponded to that of normal skin, like CD34 positivity of reticular dermis fibroblasts." (PMID 41597444, 2026). "Gene expression analysis of tumor tissue revealed that not only the expression of vascular endothelial markers such as Cd34, Pecam, and Pdgfb but also Epcam and Afp expression were decreased by DC101 treatment." (PMID 41140754, 2026). "Fibroblast-like cells of the tumor stroma were variably CD34 immunopositive only in the nodular type of BCC." (PMID 41597444, 2026). "In all examined biopsies, part of the dermis adjacent to the BCC tumor mass (juxtatumoral zone) was characterized by pronounced CD34 immunopositivity." (PMID 41597444, 2026). "The results showed that silencing miR-25 significantly upregulated E-cadherin expression while downregulating CD34 expression in tumor tissues." (PMID 40568595, 2025). "Histopathology confirmed PASH, described macroscopically as a solid, gray–yellow, encapsulated tumor and microscopically as slit-like spaces lined by spindle cells (CD34+, CD31–)." (PMID 41008766, 2025). "In either case, these data suggest the feasibility of developing xenograft (PDX) comprised of autologous tumor immunografts using CD34+ cells and a tumor from the same patient co-engrafted, and allowing for therapeutic assessment of new therapeutic modalities." (PMID 40508078, 2025). "Confirmation of the tumor’s endothelial origin inside the thymus parenchyma was established through dual immunostaining using CD34/CK HMW (34 betaE12)." (PMID 39997620, 2025). "Stromal cells lack endothelial markers (i.e., vWF, CD31, and CD34), which highlight the tumor’s vascular network." (PMID 41153937, 2025).
tumor (continued). "The results demonstrated that the IGF2 mainly expressed at CD34+CLDN5+ double positive cells in tumor tissue." (PMID 39674501, 2025). "In the immunohistochemical examination, tumor cells in SAF show immunoreactivity for CD34, EMA, and CD99." (PMID 39794215, 2025). "The results found only CD34+CLDN5+ cells were observed to be P16+P21+ and γH2AX+ positive, which prompted that the CD34+CLDN5+ ECs were senescent phenotype in tumor tissue." (PMID 39674501, 2025). "Immunohistochemistry reveals that the tumor cells exhibit varying degrees of positive CD34 expression." (PMID 41341384, 2025). "These cells exhibit significantly higher VEGF expression compared to CD34− tumor cells or normal keratinocytes." (PMID 40399946, 2025). "At 1 h, a significant portion of DCM@OPR (Purple, marked with DOX) was observed within the tumor blood vessels (Cyan, labeled with CD34)." (PMID 40102383, 2025). "Immunohistochemistry revealed tumor cells positively expressed vimentin, Cluster of Differentiation 34 (CD34), cytokeratin (CK), and CD56, while they negatively expressed insulinoma-associated protein 1 (INSM1), S100, CD68, and so on." (PMID 41244767, 2025). "Cluster of differentiation 34 (CD34) showed IHC positivity in 27 out of 45 tumor samples (60%) for which this information was available." (PMID 39853155, 2025). "Immunohistochemistry demonstrated moderate, diffuse tumor cell membrane expression of the anti-CD34 antibody." (PMID 40065864, 2025). "After integration of all samples for cluster analysis, we identified six major cell subsets in the BM, in which we observed distinct separation of HSCs/tumor cells with notable enrichment of CD34+." (PMID 41459484, 2025). "In our patient, histopathological examination confirmed the diagnosis of SFT, with the tumor exhibiting the characteristic features, including positive staining for CD34 and CD99." (PMID 40687408, 2025). "Tumor fibroblasts expressing CD34, which marks the majority of stroma in normal tissue, appeared transcriptionally similar to iCAFs." (PMID 40216939, 2025). "To investigate the role of cystatin C in human tumor development, we established a humanized mouse model by transplanting human cord blood-derived CD34+ cells into NSG-SGM3 mice." (PMID 41233352, 2025). "This facilitates tumor growth and dissemination by supplying essential nutrients and oxygen, making CD34 a promising marker for tumor development and metastasis." (PMID 39859485, 2025). "Flow cytometry of Lin-/CD34+/CD38− tumor fraction enriched for leukemic stem cells also showed similar levels of aITGB2 expression to bulk blasts." (PMID 41282197, 2025). "Immunohistochemical (IHC) staining for SMA, desmin (DES), and caldesmon (CALD1) resulted positive, demonstrating the smooth muscle lineage of the tumor, whereas CD34 highlighted only the vascular component." (PMID 39051589, 2025). "Tumor-derived granulocyte-macrophage colony-stimulating factor (GM-CSF) induces expansion of these CD34+ cells, and tumor-secreted vascular endothelial growth factor (VEGF) chemoattracts them to the tumor site." (PMID 41246358, 2025). "The lower positive rates of AFP, GPC3, GS, and CD34 in the TRG1a group further indicate a lower residual tumor burden and a more favorable tumor biology responded to conversion therapy." (PMID 41246344, 2025). "Histopathologic examination confirmed a CD34-positive spindle tumor, with immunohistochemical analysis showing that the spindle cells were positive for CD34 and negative for α-SMA, desmin, c-kit, S-100, and factor XIIIa." (PMID 40570920, 2025). "For each case, the number of CD68- and CD34-positive cells per 1.38 × 105 μm2 were measured at multiple locations in the deepest infiltration zone and tumor center, respectively, and the mean values were calculated." (PMID 40243510, 2025). "In the presence of gemcitabine, CD31 and fibronectin expression were significantly elevated in the PAK4KO tumour, while CD34 expression was decreased." (PMID 41228228, 2025).